IL22 (interleukin 22)
Diseases named in the same sentence as IL22 in open-access papers (continued):
Sharing a sentence is not in itself a finding about the gene and the disease.
enteropathy-associated T-cell lymphoma (1 paper, 2012). An uncommon mature T-cell lymphoma of intraepithelial lymphocytes. "We set out to investigate the potential use of novel serum parameters, including IL-6, IL-8, IL-17, IL-22, sCD25, sCD27, granzyme-B, sMICA and sCTLA-4 in patients diagnosed with active CD, CD on a GFD, Refractory coeliac disease (RCD) type I and II, and enteropathy associated T-cell lymphoma (EATL)." (PMID 23145841, 2012).
Erythema nodosum (1 paper, 2013). An erythematous eruption commonly associated with drug reactions or infection and characterized by inflammatory nodules that are usually tender, multiple, and bilateral. "Results showed that the expression of IL-22 mRNA in erythema nodosum skin was significantly higher in BD patients than in normal skin (p<0.001)." (PMID 23527071, 2013). "Consistent with the increased expression in skin lesions, the expression of IL-22 in the supernatants of stimulated PBMCs and the frequency of IL-22-positive CD4+ T cells in PBMCs from BD patients with erythema nodosum were also higher than the normal range." (PMID 23527071, 2013).
esophageal cancer (1 paper, 2020). A primary or metastatic malignant neoplasm involving the esophagus. "In addition, data regarding the role of systemic IL-17 or IL-22 in esophageal cancers are sparse and their clinical influence in this malignancy is unclear." (PMID 32298379, 2020). "Though, the role of circulating IL-17 or IL-22 in esophageal cancers is not yet defined and further studies are needed to clarify the role of IL-17A and IL-22 in EACs." (PMID 32298379, 2020).
Failure to thrive (1 paper, 2019). Failure to thrive (FTT) refers to a child whose physical growth is substantially below the norm. "We also show that a critical and unappreciated pathogenic mechanism triggered by IL-22 is the reduction in the expression of several pancreatic enzymes, which contributes to the failure to thrive observed in these animals." (PMID 31586069, 2019).
fulminant viral hepatitis (1 paper, 2023). Fulminant viral hepatitis is a rapid and severe impairment of liver functions (acute liver failure) with hepatic encephalopathy developing less than 8 weeks after the onset of jaundice, secondary to viral hepatitis mainly due to HBV, but also to HAV. "Further studies are required to compare the clinical manifestations and cellular responses to IL-10, IL-22, IL-26, and IFN-λ1 of patients with IL-10RB deficiency, with or without fulminant viral hepatitis." (PMID 36308662, 2023).
genital warts (1 paper, 2022). "Likewise, levels of IL-22 are increased in women with HPV-associated genital warts, thus it is likely that both, the altered bacterial communities and the presence of HPV may contribute to the elevated levels of IL-22 detected in our cohort." (PMID 35656032, 2022).
glomerular disease (1 paper, 2020). "Though a regenerative potential of IL-22 in renal tubular injury is well-defined, however, in glomerular disease, redundancy in IL-22 expression was observed." (PMID 33042126, 2020).
gout (1 paper, 2021). A condition characterized by painful swelling of the joints, which is caused by deposition of urate crystals. "Remarkably, this study showed that mRNA expression levels of IL-22 were higher in the acute and remission phases of gout." (PMID 34917427, 2021). "In summary, this study reported the involvement of IL-22 and VD3 in inflammation associated with gout pathogenesis." (PMID 34917427, 2021). "In summary, these results agreed that IL-22 and VD-R play functionally important roles in the inflammatory response and are therefore relevant to gout pathogenesis." (PMID 34917427, 2021). "In order to further investigate the function of IL-22 and VD-R in the pathogenesis of gout, a complex protein-protein interaction network was constructed using Search Tool for the STRING." (PMID 34917427, 2021). "Therefore, further studies are required to confirm the mechanisms via which 1,25 (OH)2VD3 affects the secretion of IL-22 in gout." (PMID 34917427, 2021). "What’s more, serum VD-R and IL-22 were increased in patients and may be involved in the pathogenesis of gout arthritis via influencing the uric acid level of gout patients that both VD-R and IL-22 closely correlated with the level of uric acid of GA patients." (PMID 34917427, 2021). "Finally, the biological functions of 1,25(OH) 2 VD3 and IL-22 in gout pathogenesis were further explored via bioinformatics analysis, and the detailed variations in metabolic pattern of GA were displayed by metabolomics profiles." (PMID 34917427, 2021). "In this study, levels of IL-22 in plasma were increased in both acute and chronic gout patients." (PMID 34917427, 2021). "This indicates that IL-22 was involved in the pathogenesis of gouty arthritis." (PMID 34917427, 2021). "In this study, we hypothesize that IL-22, is correlated with the occurrence and development of gout." (PMID 34917427, 2021). "However, our understanding of the responses of 1,25(OH) 2VD3 and IL-22 to gout was still unclear." (PMID 34917427, 2021). "Overall, IL-22, VD-R and 1,25(OH) 2 VD3 play functionally important roles in inflammatory responses and are relevant to gout pathogenesis." (PMID 34917427, 2021). "Remarkably, the levels of IL-22 were shown to be higher in patients with gouty arthritis in either the acute phase or non-acute phase in comparison to healthy controls." (PMID 34917427, 2021). "However, the role of IL-22 and VD3 in gout pathogenesis is yet to be elucidated." (PMID 34917427, 2021). "Furthermore, the levels of IL-22 and VD3 correlated with that of CRP in gout patients." (PMID 34917427, 2021).
Graves disease (1 paper, 2025). Graves' disease is an autoimmune disorder that leads to overactivity of the thyroid gland (hyperthyroidism).It is caused by an abnormal immune system response that causes the thyroid gland to produce too much thyroid hormones. "Serum cytokine levels (including IL-6, IL-9, IL-17A, IL-17F, and IL-22) exhibited significant differences between healthy subjects and patients with newly diagnosed hyperthyroid Graves’ disease (GD) under varying serum iodine concentration (SIC)." (PMID 40895623, 2025).
Headache (1 paper, 2021). Cephalgia, or pain sensed in various parts of the head, not confined to the area of distribution of any nerve. "Regarding the central tendency measures, in the comparison of the crude median values of cytokines, we observed that patients with headache had higher median values of GROa, IFN-gamma, IL-10, IL-13, IL-15, IL-17a, IL-21, IL-22, IL-27 and IL-6." (PMID 34088273, 2021).
herpesvirus infection (1 paper, 2014). "Our data identify a role for neutrophils in antiviral defense, and establish a functional link between IL-22 and the control of antiviral neutrophil responses that prevents pathogenic herpesvirus infection in peripheral organs." (PMID 24721575, 2014). "Our results reveal a previously unanticipated mechanism through which IL-22 impacts on virus-induced immune responses and a potent effector mechanism that counters herpesvirus infection." (PMID 24721575, 2014).
hyperlipidemia (1 paper, 2025). "Hyperlipidemia is associated with depletion of circulating ILC3s and reduced IL-22." (PMID 41415268, 2025). "Peripheral ILC subsets and plasma IL-22 were assessed in hyperlipidemia patients and healthy controls." (PMID 41415268, 2025). "Plasma IL-22 levels were significantly reduced in hyperlipidemia patients compared to healthy controls (49.86 [27.62–103.27] pg/ml vs. 103.95 [57.61–245.27] pg/ml, p=0.001)." (PMID 41415268, 2025). "Hyperlipidemia was characterized by reduced circulating ILC3s, integrin α4+ ILC3s, and plasma IL-22, all of which showed inverse correlations with TC, TG, LDL-C, non-HDL-C, and ApoB." (PMID 41415268, 2025). "In our cohort, plasma IL-22 levels were significantly reduced in hyperlipidemia and inversely correlated with TC, TG, non-HDL-C, and ApoB, while positively associated with HDL-C." (PMID 41415268, 2025).
hyperthyroidism (1 paper, 2025). Overactivity of the thyroid gland resulting in overproduction of thyroid hormone and increased metabolic rate. "Nevertheless, limited data exist regarding IL-22’s involvement in hyperthyroidism development under high-iodine conditions." (PMID 40895623, 2025).
Hypothermia (1 paper, 2017). Reduced body temperature due to failed thermoregulation. "Hypothermia may thus be able to inhibit additional signals that are required for IFNγ production but leave IL-22 unaffected." (PMID 28706520, 2017).
ichthyoses (1 paper, 2023). "The results indicated activation of IL-17/IL-22 in peripheral blood through ichthyosis." (PMID 38027029, 2023). "The authors observed raised IL-17 and IL-22 in all ichthyoses, as in the two previous studies." (PMID 38027029, 2023).
infectious kidney diseases (1 paper, 2022). "Because IL-22 is able to protect against pathogenic bacterial infections, promote cell proliferation, inhibit apoptosis, and suppress oxidative stress, we propose an attempt to apply IL-22 or its fusion proteins in infectious kidney diseases and AKI." (PMID 35432360, 2022). "Similarly, IL-22 is critical for limiting bacterial replication and hematogenous dissemination in renal infectious diseases, possibly in part by inducing the expression of antimicrobial peptides in epithelial cells on the surface of these barriers." (PMID 35432360, 2022).
intestinal cancer (1 paper, 2025). "IL-22 enhances intestinal barrier function and promotes the production of antimicrobial proteins, which may be protective against the development of intestinal cancers in some cases." (PMID 41019044, 2025).
invasive breast carcinoma (1 paper, 2025). A carcinoma that infiltrates the breast parenchyma. "Similar to IL-21, our results showed changes in the IL-22 levels in patients with invasive breast cancer." (PMID 40729006, 2025). "This preliminary study did not reveal statistically significant differences in serum IL-21 and IL-22 levels between patients with invasive breast cancer and those with benign breast lesions." (PMID 40729006, 2025).
invasive carcinoma (1 paper, 2020). A carcinoma that is not confined to the epithelium, and has spread to the surrounding stroma. "A significant increase in the levels of IL‐22 was noticed from the early carcinoma stage through the advanced invasive carcinoma stage (8–10 weeks) of disease progression." (PMID 31725949, 2020).
laryngeal carcinoma (1 paper, 2021). Carcinoma that arises from the laryngeal epithelium. "This study suggested IL-22 and IL-22R1 play an important role in the pathogenesis of laryngeal carcinoma." (PMID 34941188, 2021).
lichen planus (1 paper, 2020). A chronic, recurrent, pruritic inflammatory disorder of unknown etiology that affects the skin and mucus membranes. "Serum samples were preparedfrom patients with lichen planus and IL-22 concentration was measured in each serum sample by using a commercial ELISA Kit." (PMID 33344684, 2020).
liposarcoma (1 paper, 2011). A usually painless malignant tumor that arises from adipose tissue. "We found that phosphorylated ERK level was markedly elevated in the tumors of IL-22-TG mice, indicating that Ras to ERK signaling pathway might be also implicated in the formation of spontaneous liposarcomas in IL-22-TG mice." (PMID 21897855, 2011). "Intriguingly, high fat diet is a premise for the development of spontaneous liposarcomas in IL-22-TG mice." (PMID 21897855, 2011). "However, the IL-22 transgenic mice developed spontaneous liposarcomas in adipose tissue after long-term feeding with high fat diet, indicating that diet may interact with inflammation changes associated with IL-22 overexpression in tumorigenesis in adipose tissue." (PMID 21897855, 2011). "In addition, we observed an increased level of ERK phosphorylation both in mouse liposarcoma samples and IL-22-treated adipocytes." (PMID 21897855, 2011). "However, high fat diet together with IL-22 overexpression could induce formation of spontaneous liposarcomas in adipose tissue with 100% penetrance." (PMID 21897855, 2011). "Collectively, these findings indicate that IL-22-induced expression of inflammatory cytokines and activation of ERK may contribute to the formation of spontaneous liposarcomas in IL-22-TG mice fed with HFD." (PMID 21897855, 2011). "In addition, we analyzed the mRNA level of MDM2 gene, a key feature of well-differentiated liposarcoma, and found that MDM2 expression was markedly elevated in the adipose tumors in IL-22-TG mice fed with HFD (data not shown)." (PMID 21897855, 2011).
lymph node metastasis (1 paper, 2021). "The expression of IL-22 and IL-22R1 was significantly related to lymph node metastasis (P = .002, P = .009) and clinical stage of LSCC (P = .001, P = .037)." (PMID 34941188, 2021).
lymph node tuberculosis (1 paper, 2022). Tuberculosis of the lymph node. "IL-22 has positive roles, such as stimulating tissue repair, even in cases of challenging wounds (for example, in diabetic patients or patients diagnosed with lymph node tuberculosis)." (PMID 35409053, 2022).
Lymphadenopathy (1 paper, 2021). Enlargement (swelling) of a lymph node. "The score of lymphadenopathy in control mice was significantly increased compared to IL-22 KO mice, and also higher than that in IL-22R KO mice though without significant difference." (PMID 33717066, 2021).
Lymphatic Metastasis (1 paper, 2021). Transfer of a neoplasm from its primary site to lymph nodes or to distant parts of the body by way of the lymphatic system. "The expressions of IL-22 and IL-22L were significantly different in the cases of lymphatic metastasis and clinical stage." (PMID 34941188, 2021).
lymphedema (1 paper, 2009). Excess fluid collection in tissues, causing swelling. "To address the role of Th17 cells in filarial lymphedema, we examined the expression of IL-17A, IL-17F, IL-21 and IL-22 as well as the upstream inducing cytokines IL-23, IL-6 and IL-1β in PBMCs of lymphedema patients following BmA or PPD stimulation." (PMID 19381284, 2009). "Most effector cytokines known to be produced by Th17 cells—IL-17A, IL-17F, and IL-21 (with the exception of IL-22)—are induced at significantly higher levels in patients with lymphedema, suggesting an important role for these cytokines in development of this disease process." (PMID 19381284, 2009).
malnutrition (1 paper, 2021). Inadequate nutrition resulting from poor diet, malabsorption, or abnormal nutrient distribution. "Protein levels of IL-17A (p < 0.05), IL-21 (p < 0.05), and IL-22 (p < 0.05) were significantly increased in the LP and LPi mice due to malnutrition." (PMID 34207946, 2021). "Increased levels of duodenal IL-17A, IL-21, IL-22, CXCL5 due to malnutrition—together with decreased levels of TNFα, IL-12, TGFβ and CXCL10 and elevated levels of IgA due to infection—revealed that the duodenum was sensitive to both variables and suggested local inflammation in malnourished animals." (PMID 34207946, 2021).
metastatic disease (1 paper, 2020). "MBC patients’ exosomes had a low concentration of MIP-3 alpha, IL-23, M-CSF, Eotaxin-3, BLC, SDF-1 alpha, IL-2R, MDC, FGF-2, IL-22, and IL-31, suggesting that metastatic disease may be associated with immune suppression related to low exosomal cytokines." (PMID 32826923, 2020).
Miscarriage (1 paper, 2019). A pregnancy that ends at a stage in which the fetus is incapable of surviving on its own, defined as the spontaneous loss of a fetus before the 22th week of pregnancy. "In addition, IL-22 could be beneficial for pregnancy by protecting trophoblast from pathogens, which cause a fivefold increase in the number of miscarriages in virtue of its ability to induce the secretion of antimicrobial peptides locally." (PMID 30669479, 2019). "Because of this, IL-22 produced by CD4+ T cells from decidua could be a factor responsible for miscarriage." (PMID 30669479, 2019). "IL-22 seems to be involved in allograft rejection and thus could be responsible for miscarriages." (PMID 30669479, 2019).
multinodular goiter (1 paper, 2021). Nodular goiter characterized by more than one discrete tissue mass. "The sample from patient #87 (female, 56 years old) with diagnosed primary hyperparathyroidism and multinodular goiter contained autoantibodies against IL-22." (PMID 34071130, 2021).
myositis (1 paper, 2019). "Yet lately the recognition of Th17-associated cytokines such as IL-17, IL-22, and IL-6 in the blood and other areas of inflammation in some patients with myositis has challenged our current knowledge on the etiopathology of myositis." (PMID 31429786, 2019). "However, in the last decade overexpression and elevated level of Th17-associated cytokines (IL-17, IL-22, and IL-6) were identified in the blood and the inflamed muscles of myositis patients." (PMID 31429786, 2019).
nematode infection (1 paper, 2019). "Moreover, IL-22 has been shown to induce goblet cell hyperplasia in nematode infection." (PMID 31311100, 2019).
neuromyelitis optica (1 paper, 2015). A rare inflammatory disease of the central nervous system characterized mainly by attacks of uni- or bilateral optic neuritis (ON) and acute myelitis. "Similarly to us, others recently found that CD4+ T cells, and more specifically Th17 and Th22 cells, of MS and neuromyelitis optica (NMO) patients secreted more IL-22 than those of HC." (PMID 26077779, 2015).
non-Hodgkin lymphoma (1 paper, 2022). Distinct from Hodgkin lymphoma both morphologically and biologically, non-Hodgkin lymphoma (NHL) is characterized by the absence of Reed-Sternberg cells, can occur at any age, and usually presents as a localized or generalized lymphadenopathy associated with fever and weight loss. "It was previously reported that a significant portion of mononuclear cells in salivary glands of SS patients, and those in the non-Hodgkin’s lymphoma (NHL) lesions of SS patients, can produce IL-22; it will be interesting to examine if some of these IL-22-producing cells in SS patients are B cells." (PMID 36361787, 2022).
non-melanoma skin carcinoma (1 paper, 2017). "Elevated IL-22 expression has been detected in several human tumors, including ovarian, prostate, breast, hepatocellular, esophageal, gastric, and non-melanoma skin cancers." (PMID 29262587, 2017).
osteoporosis (1 paper, 2016). A condition of reduced bone mass, with decreased cortical thickness and a decrease in the number and size of the trabeculae of cancellous bone (but normal chemical composition), resulting in increased fracture incidence. "Our findings are in line with the already identified role of IL-20 in osteoporosis and the established association between the IL-22-IL-22R system and bone degradation in RA." (PMID 26968800, 2016).
ovarian serous cancer (1 paper, 2021). "The aim of the analysis was for the first time to assess the expression of genes encoding IL-21 and IL-22 at the mRNA level in ovarian tumor specimens and the concentration of these parameters in serum and peritoneal fluid in patients with ovarian serous cancer." (PMID 34300224, 2021).
ovarian tumor (1 paper, 2021). "For the first time, the expression of genes encoding IL-21 and IL-22 was assessed at the mRNA level in ovarian tumor specimens." (PMID 34300224, 2021).
overactive bladder (1 paper, 2014). Symptom of overactive detrusor muscle of the urinary bladder that contracts with abnormally high frequency and urgency. "IL22 could serve as a regulatory cytokine that contributes to the physiopathology of overactive bladder by modulating the acetylcholine response through inhibition MR1 expression." (PMID 25354343, 2014).